FLT3 (fms related receptor tyrosine kinase 3)
Diseases named in the same sentence as FLT3 in open-access papers (continued):
Sharing a sentence is not in itself a finding about the gene and the disease.
cancer (continued). "Therefore, cancer‐related RTK become preferable targets for ADC development, e.g. RON, PTK7, FLT3, FGFR2, FGFR3, ERBB3, KIT and EPHA2." (PMID 31116512, 2019). "Combined inhibition of FLT3 and CDK6 reduced the severeness of cancer-promoting processes, but could still be bypassed by PI3K-mediated signalling involving the nodes PI3K, SHC and AXL resulting in potential treatment escape routes." (PMID 29699481, 2018). "Although inhibition of autophagy itself is not sufficient to induce cancer cell death, Yuan's team demonstrated that inhibition of the receptor tyrosine kinase FLT3 signalling in non-hematopoietic cancers renders them sensitive to CMA inhibition." (PMID 26938302, 2016). "A674563 exhibits potent activity against FLT3-ITD positive AML cancer cells in vitro and in vivo through selective, dual inhibition of AKT and FLT3 kinases, and is also capable of overcoming FLT3 ligand-induced drug resistance in FLT3 wt/ITD co-expressing cells." (PMID 27074558, 2016). "An association between germline mutations of four genes (FLT3, HOXD11, TCF3, and ATP1A1) and cancer has not been reported." (PMID 27701467, 2016). "In summary, we have discovered that A674563, a previously reported AKT kinase inhibitor, also demonstrates selective FLT3-ITD kinase activity over FLT3 wt in the biochemical assays, which makes it selectively potent toward FLT3-ITD positive AML cancer cell lines." (PMID 27074558, 2016). "When using SNVs only, most such genes were known cancer genes, such as U2AF1, IDH1, and DNMT3A in LAML (FLT3 SNVs cluster within five amino acids), AKT1 and KRAS in BRCA, BRAF and KRAS in COADREAD, IDH1 and PARG (poly (ADP-ribose) glycohydrolase) in GBM, and KRAS in UCEC." (PMID 25348067, 2014). "Among nine cancer-associated mutations that determine sensitivity to ATRA (Notch 1, BCR_ABL, KIT, FLT3, APC, TET2, K-ras, ALK, MLL_AFF1), KRAS, APC, and KIT mutations are associated with resistance to ATRA (only K-ras is shown)." (PMID 23982413, 2013). "The current results corroborate a role of PRL-3 in FLT3-ITD-driven AML progression and indicate a novel use of PRL-3 antibody therapy to treat PRL-3 positive AML patients, in addition to other PRL-3-positive cancer types previously investigated." (PMID 23929599, 2013). "FLT3 is one of the genes related to the ERK signaling pathway, and PLX3397, whichtargets FLT3, may indirectly inhibit the ERK1/2 signaling pathway, which plays a key role in cancer development and progression." (PMID 39132250, 2024). "However, whether the mechanisms of CiPSC and adipocyte reprogramming are similar to that in cancers (i.e., via inhibition of VEGF/PDGFR/CSF-1F/FLT3) requires further investigation." (PMID 37264282, 2023). "There were more FLT3, FGFR1, and AKT1 mutations (p-value < 0.05) in nonhypermutated cancers, while there were more RET, CBL, and DDR2 mutations (p-value < 0.05) in hypermutated cancers." (PMID 34503126, 2021). "In addition, a Boolean model derived from a smaller network-module representing the crosstalk between FLT3, DNMT3A, NPM1 and cancer hallmarks, when primed with patient-specific genomic profiles, yielded predictions that are in accord with patients’ clinical data." (PMID 33578936, 2021). "To ask whether FLT3-ITD cells are dependent of CDC25A activity for their proliferation, we first used IRC-083864, a potent pharmacological inhibitor of CDC25 (A, B and C) previously characterized in vitro and in vivo in different cancer models." (PMID 26515730, 2015). "These malignancies are also likely to benefit from the development of newer generation Mer inhibitors with improved in vivo bioavailability for use in the treatment of human disease, though it is not clear if these cancers would equally benefit from the dual Mer/Flt3 inhibition." (PMID 25762638, 2015).
cancer (continued). "While numerous clinical studies have targeted NRF2 across various cancer types over the past three decades, none have specifically focused on FLT3-mutant AML, despite evidence suggesting that targeting NRF2 and antioxidant pathways may deplete leukemic stem cells (LSCs)." (PMID 41003134, 2025). "Hence, the gene expression inference from our nucleosome positioning mapping approach suggested that our observations from the cell culture systems are applicable to these clinical cases and, furthermore, that FLT3 is indeed not the cancer driver gene within this amplicon in CRC." (PMID 32087735, 2020). "In addition, histone deacetylase inhibitors (HDACi), a class of compounds that can induce cancer cell growth arrest and cell death by altering the acetylation status of both histone and non-histone proteins, can enhance the activity of FLT3 inhibitors on AML cell apoptosis." (PMID 24416160, 2014). "Thus, we conclude that the FLT3 inhibitor tandutinib can reverse MRP7-mediated MDR through inhibition of the drug efflux function and may have potential to be used clinically in combination therapy for cancer patients." (PMID 23525656, 2013). "Nearly 80% or more of SNVs in FLT3, PDGFRA, PGR, and RET were not expressed among all cancer patients." (PMID 29721196, 2018). "However, reports regarding PFGFRA, HRAS, AKT1, FLT3, and NOTCH1 are lacking in the TCGA tonsil cancer data." (PMID 36979829, 2023). "Using PPI analysis, the critical pathway of functional genes was found involved in the hematopoietic cell lineage and transcriptional misregulation in cancer, including HOXA10, MEIS1, FLT3, CD14, PROM1, RUNX2, and RUNX1 (data not shown), indicating the dominant roles of HOXA and MEIS1 in MLL-R ALL." (PMID 36276286, 2022).
hematologic malignancies (41 papers, 2010 to 2026). "Activating the mutation of D835 within the activation loop of FLT-3 in human hematologic malignancies leads to persistent activation of the FLT-3 receptor." (PMID 34020686, 2021). "ITD or TKD mutations in the FLT3 gene show the potential to induce different hematologic malignancies." (PMID 34944812, 2021). "Our results strongly suggest that pre-transplant detection of FLT3/ITD mutation by PCR may serve as a reliable MRD marker which predicts post-transplant outcome better than the hematological disease status." (PMID 32333156, 2020). "PIM1, a serine/threonine kinase, is known to be overexpressed predominantly in hematologic malignancies and is a downstream target of HOXA9, especially in AML with FLT3-ITD mutations." (PMID 40746924, 2025). "The ORRs of FLT3 inhibitors in hematologic malignancies and solid tumors were 40.8% and 18.8%, respectively, indicating FLT3 inhibitors were more effective for hematologic malignancies than for solid tumors." (PMID 38828446, 2024). "CCDC88C encodes a protein part of the Wnt signaling pathway and has previously been described in hematological malignancies as fusion partner to FLT3 and PDGFRB." (PMID 36704135, 2023). "FLT3 belongs to the receptor tyrosine kinase family, which is more widely reported in hematological diseases." (PMID 35813858, 2022). "Sunitinib has been proposed as a potential candidate to treat FLT3-driven hematological malignancies, an alteration that is present in the SEM cell line." (PMID 34568318, 2021). "Due to the important role of FLT3 in hematological disorders, applications of targeted therapies including FLT3 inhibitors and tyrosine kinase inhibitors have been developed to inhibit the activation of FLT3." (PMID 34194582, 2021). "FLT3, as one of the most meaningful oncogenes in hematological malignancies, is involved in this amplification." (PMID 34194582, 2021). "Since FLT3 is a well-known driver gene in hematological malignancies that can be targeted by the drug sorafenib, FLT3 was considered to be a reasonable driver candidate." (PMID 32087735, 2020). "Mutations in the FLT-3 gene have been found in patients with ALL (1–3%), myelodysplasia (5–10%), and AML (15–35%), making it one of the most frequently mutated genes in hematologic malignancies." (PMID 32718354, 2020). "The distinction between a cell-intrinsic or -extrinsic effect of Flt3-ITD on the HSC compartment is of considerable importance for understanding the role of Flt3 in normal hematopoiesis and the impact of Flt3-ITDs on HSCs in hematologic malignancies." (PMID 28637883, 2017). "Gain-of-function mutations of the FLT3, KIT and PDGFR class III receptor tyrosine kinases (RTK) play important roles as oncogenesis-driving events in several hematologic malignancies." (PMID 23497317, 2013). "In hematological malignancies, OC may enhance FLT3 and Bcl-2 inhibitor responses by disrupting survival signals and inhibiting MCL-1." (PMID 40564985, 2025). "Intriguingly, in comparison to the previous analysis, we observed 6 new non-synonymous SNVs linked to hematological disease, including variations in CBL (1 pt); DNMT3A (3 pts); FLT3 (1 pts), NQO1 (1 pt); NRAS (1 pts) and 2 frameshifts: CEBPA (1 pts) and NBN (1 pts)." (PMID 38612443, 2024). "However, our data supported an effect of SYK inhibition particularly in FLT3 mutated cases, and special TAK-659, which has inhibitory effects against both FLT3 and SYK, seems promising for use in hematological malignancies." (PMID 36499034, 2022). "In hematological malignancies, MUC1-C has been associated with various pathways related to disease pathogenesis, such as Wnt/β-catenin, fms-like tyrosine kinase 3 (FLT3), breakpoint cluster region protein (BCR)/Tyrosine-protein kinase (ABL), and NF-κB, which are involved in tumorigenesis." (PMID 34207342, 2021).
hematologic malignancies (continued). "Analogous to the triple combination of HMA, venetoclax and FLT3 inhibitor as targeted agent for FLT3-mutated AML, the combination of azacitidine, venetoclax, and ivosidenib is under investigation for IDH1-mutated hematologic malignancies in an early-phase clinical trial (NCT03471260)." (PMID 33958699, 2021). "In addition, both the FLT-3 PROTAC and inhibitor were ineffective against other types of hematologic malignancies, such as K562 CML cells, suggesting that the antitumor effect of the FLT-3 PROTAC on different FLT-3 ITD mutated cells is cell-dependent." (PMID 32718354, 2020). "Thus, FLT-3 has been emerged as a therapeutic target for hematologic malignancies." (PMID 32718354, 2020). "Distinguishing between a cell-extrinsic and -intrinsic impact of Flt3-ITD on HSCs is crucial, as it has extensive implications for the understanding of Flt3 as a key regulator of normal hematopoiesis and the impact and therapeutic targeting of FLT3-ITD mutations in hematologic malignancies." (PMID 28637883, 2017). "Higher response rates against hematologic malignancies were observed, in particular when the Aurora inhibitor exhibited a secondary anticancer pharmacology; for example, the inhibition of another oncogenic driver of hematologic cancers such as activated FLT3 in AML." (PMID 26734566, 2015). "Small molecule inhibitors targeting cellular oncoproteins and enzymes such as BCR-ABL, JAK2, Bruton tyrosine kinase, FLT3, BCL-2, IDH1, IDH2, are biomarker-driven chemotherapy-free agents approved for several major hematological malignancies." (PMID 33879198, 2021). "Genomic characterization of pediatric hematologic malignancies in our cohort identified potential therapeutic targets in nearly 40% of patients (7/18, 38.9%), including the consideration of inhibitors targeting MEK (n=3), receptor tyrosine kinases (ALK n=2, PDGFRB n=1), FLT3 (n=1), and PD-L1 (n=1)." (PMID 39687881, 2024). "However, no exhibited amplification of FLT3 on dmins has been reported in hematological malignancies." (PMID 34194582, 2021). "Genomic amplification of FLT3 has not been reported in hematological disease." (PMID 34194582, 2021).
infection (18 papers, 2010 to 2025). The state of being infected such as from the introduction of a foreign agent such as serum, vaccine, antigenic substance or organism. "FLT3 inhibitors may also be beneficial for patients with FLT3 mutation or overexpression where high-dose chemotherapy is contraindicated, such as in cases of infection or toxicity." (PMID 39711880, 2024). "Tyrosine kinase inhibitors targeting FLT3 improved the prognosis of patients with AML but also increased infection rates." (PMID 39518156, 2024). "Because there was an increase in extrapulmonary CFSE– Mks during PYnL infection, we assessed whether Mks that migrate to the lung arise from Flt3– progenitors." (PMID 39302653, 2024). "There were also two DC related genes that showed significant difference between O1 and O2 (FLT3 and CCR7); these were downregulated following both APEC O1-GFP and APEC O2-GFP infection, but to a greater extent in the APEC O2-GFP infected cells." (PMID 31998322, 2019). "Transcription levels of the myeloid-associated genes C/EBPα, PU.1, FOG1, and G-CSF were increased in total BM cells by 2–3-fold at 12 h post infection, while transcription levels of the lymphoid-associated genes IL7-R, Flt3, Rag1, PAX5, and Ikaros did not change at this time point." (PMID 23189271, 2012).
hematopoietic cancer (15 papers, 2015 to 2025). "Collectively,these findings demonstrate the ability of ReSisTrace to unveil pre-existingtranscriptional features of treatment vulnerability in hematological cancers andelucidate strategies for enhancing FLT3 inhibitor treatment efficacy inFLT3-ITD-mutated AML." (PMID 41270153, 2025). "Many CIS occurred near genes implicated in hematologic cancers and hematopoietic development (Erg, Ets1, Epo, Il2rb, Flt3, Kras, Stat5b, Fli1)." (PMID 30940846, 2019). "Anomalies in FLT3 have an established role as a therapeutic target where the gene has been shown to play a critical role in the growth, differentiation, and survival of various cell types in hematopoietic cancer and have shown promise in various solid tumors." (PMID 37174019, 2023). "To determine whether CDK6 is a common essential effector of oncogenic tyrosine kinases, we evaluated its contribution downstream of oncogenic KIT, a receptor closely related to FLT3 also involved in hematopoietic neoplasms." (PMID 27323399, 2016). "FMS-like tyrosine kinase 3 (FLT3) is a well-known marker in AML and its overexpression has been found in other hematological cancers, including ALL." (PMID 34572272, 2021). "By examining statistical independence between pairwise dependency profiles, we identify additional pairs of proteins that share short loop commonality and exhibit either mutual exclusivity (as does FLT3 and KIT) or co-occurrence of dependency in haematopoietic cancer cell lines." (PMID 33709075, 2021). "Indeed, the concomitant blockade of Fms-like tyrosine kinase 3 (FLT3) using Quizartinib (a tyrosine kinase inhibitor) and MA by means of small molecules (C43 or TAK-165) identified in a functional screen triggered HK2 degradation and metabolic catastrophe in solid and hematopoietic cancer cells." (PMID 31623164, 2019).
blood cancers (10 papers, 2020 to 2025). "The cellular consequences of activating FLT3 mutations in blood cancers are poorly understood." (PMID 38724759, 2024). "Of note, FLT3/ITD+ AML represents one of the most aggressive forms of blood cancer and carries a dismal prognosis due to short remission durations and high relapse rates." (PMID 34791807, 2021). "Agents worth testing in combination studies include FLT3 inhibitors in AML, BCR signaling inhibitors in certain NHL subtypes, and BH3 mimetic drugs (BCL2 inhibitor venetoclax and MCL-1 inhibitors) in a variety of blood cancers." (PMID 34408976, 2021).
neurodevelopmental disorder (3 papers, 2023 to 2026). A behavioral and cognitive disorder with onset during the developmental period that involves impaired or aberrant development of intellectual, motor, or social functions. "Replication in a person who stutters is required to confirm that stuttering is a feature of the monogenic neurodevelopmental disorders associated with mutations in SPTBN1, PRPF8, TRIO, and ZBTB7A, and to causally link FLT3 and IREB2 to neurodevelopmental disorders." (PMID 40836029, 2026). "Genes of interest FLT3 and IREB2 have not been associated with a neurodevelopmental disorder." (PMID 40836029, 2026). "Further investigating the role of FLT3+IBA1+ cells in remodeling of specific synaptic networks and their relationship with neuronal progenitors could be the next step toward using these cells in cellular therapy for neurodevelopmental disorders." (PMID 39021809, 2024).
inflammation (2 papers, 2020 to 2025). Aberrant reaction of the microcirculation characterized by movement of fluid and leukocytes from the blood into extravascular tissues. "For instance, the inhibition of FLT3 signal transduction by lestaurtinib can alleviate LPS-induced acute pulmonary inflammation and injury." (PMID 40362543, 2025). "Collectively, these findings are important because they provide evidence that Flt3 is required to control type 2 allergic inflammation." (PMID 33327561, 2020). "Our findings suggest that Flt3 is required to control type 2 allergic inflammation." (PMID 33327561, 2020).
kidney disease (2 papers, 2017 to 2021). "Therefore, CD103+ DCs are critically dependent on Flt3, and the development of CD103+ DCs is more strongly inhibited in Flt3- and Flt3L-deficient mice than other subsets of DCs, suggesting Flt3 inhibition can be an option to suppress cDC1s activity in the kidney disease." (PMID 34299173, 2021).
infectious disease (1 paper, 2025). A disorder directly resulting from the presence and activity of a microbial, viral, or parasitic agent in humans. "In addition, 3 died from infectious diseases at 1 month (VSAA with WTI variant), 3 months (VSAA with FLT3 variant), and 9 months (VSAA with ASXL1 and IDH1 variant) after diagnosis." (PMID 41477271, 2025).
neurological diseases (1 paper, 2025). "Additionally, our findings uncover a previously unrecognized neuron-specific pattern of Flt3 expression in the cerebellum, laying the foundation for future mechanistic studies on its role in normal brain development and neurological disorders." (PMID 40076904, 2025). "Pharmacological inhibition of Flt3 has been associated with increased KCC2 expression, a chloride transporter critical for GABAergic inhibition, which indicates potential treatment of neurological disorders." (PMID 40076904, 2025).
retinopathy (1 paper, 2018). "Our study highlights Flt3 as a novel molecular target for the inhibition of neovascularization in murine models of retinopathy." (PMID 29854425, 2018).
FLT3 also shares sentences with these, for which no sentence is quoted: acute T-lymphoblastic leukemia (3 papers); diffuse large B-cell lymphoma (3); Hand-foot syndrome (3); lymphoid neoplasm (3); Stroke (3); Wilms' tumour (3); acute myelomonocytic leukemia (2); Cognitive impairment (2); colon (2); Erythema (2); graft versus host disease (2); head and neck cancer (2); heart failure (2); leukopenia (2); mantle cell lymphoma (2); mast cell leukemia (2); pneumonia (2); renal carcinoma (2); skin cancer (2); squamous cell carcinoma (2); Thrombocytosis (2); acute lung injury (1); acute myocardial infarction (1); alopecia (1); Alzheimer disease (1); amyotrophic lateral sclerosis (1); aneurysm (1); angioimmunoblastic T-cell lymphoma (1); apraxia of (1); aspergillosis (1).
A further 89 diseases each share a sentence with FLT3 in 1 paper.